HAP1 (huntingtin associated protein 1)
Description:
Originally identified as neuronal protein that specifically associates with HTT/huntingtin and the binding is enhanced by an expanded polyglutamine repeat within HTT possibly affecting HAP1 interaction properties. Both HTT and HAP1 are involved in intracellular trafficking and HAP1 is proposed to link HTT to motor proteins and/or transport cargos. Seems to play a role in vesicular transport within neurons and axons such as from early endosomes to late endocytic compartments and to promote neurite outgrowth. The vesicular transport function via association with microtubule-dependent transporters can be attenuated by association with mutant HTT. Involved in the axonal transport of BDNF and its activity-dependent secretion; the function seems to involve HTT, DCTN1 and a complex with SORT1. Involved in APP trafficking and seems to facilitate APP anterograde transport and membrane insertion thereby possibly reducing processing into amyloid beta. Involved in delivery of gamma-aminobutyric acid (GABA(A)) receptors to synapses; the function is dependent on kinesin motor protein KIF5 and is disrupted by HTT with expanded polyglutamine repeat. Involved in regulation of autophagosome motility by promoting efficient retrograde axonal transport. Seems to be involved in regulation of membrane receptor recycling and degradation, and respective signal transduction, including GABA(A) receptors, tyrosine kinase receptors, EGFR, IP3 receptor and androgen receptor. Among others suggested to be involved in control of feeding behavior (involving hypothalamic GABA(A) receptors), cerebellar and brainstem development (involving AHI1 and NTRK1/TrkA), postnatal neurogenesis (involving hypothalamic NTRK2/TrkB), and ITPR1/InsP3R1-mediated Ca(2+) release (involving HTT and possibly the effect of mutant HTT). Via association with DCTN1/dynactin p150-glued and HTT/huntingtin involved in cytoplasmic retention of REST in neurons. May be involved in ciliogenesis. Involved in regulation of exocytosis. Seems to be involved in formation of cytoplasmic inclusion bodies (STBs). In case of anomalous expression of TBP, can sequester a subset of TBP into STBs; sequestration is enhanced by an expanded polyglutamine repeat within TBP. HAP1-containing STBs have been proposed to play a protective role against neurodegeneration in Huntigton disease (HD) and spinocerebellar ataxia 17 (SCA17).
Synonyms: HAP2; HLP; hHLP1; HIP5
Tractability: PROTAC: its protein half-life has been measured.
Gene: Protein-coding gene on chromosome 17 (41,717,742 to 41,734,644, reverse strand). Ensembl gene ENSG00000173805.
Subcellular location: Cytoplasm; Cell projection, axon; Presynapse; Cytoplasm, cytoskeleton; Cell projection, dendritic spine; Cell projection, dendrite; Lysosome; Endoplasmic reticulum; Mitochondrion; Nucleus; Cytoplasmic vesicle, autophagosome; Early endosome; Cell projection, growth cone; Cell projection, neuron projection; Cytoplasmic vesicle, secretory vesicle, synaptic vesicle
Subcellular location (Human Protein Atlas): Cytosol; Nucleoli
Gene Ontology:
Molecular function: protein binding; brain-derived neurotrophic factor binding; myosin binding; signaling receptor binding; transmembrane transporter binding
Biological process: intracellular protein localization; anterograde axonal transport; brain development; chemical synaptic transmission; mitochondrion distribution; negative regulation of amyloid-beta formation; neurogenesis; neurotrophin TRK receptor signaling pathway; positive regulation of calcium-mediated signaling; positive regulation of epidermal growth factor receptor signaling pathway; positive regulation of neurotrophin production; positive regulation of non-motile cilium assembly; positive regulation of synaptic transmission, GABAergic; protein targeting; regulation of exocytosis; regulation of organelle transport along microtubule; retrograde axonal transport; vesicle transport along microtubule; cerebellum development; hypothalamus cell differentiation; positive regulation of neurogenesis
Cellular component: cytosol; inclusion body; actin cytoskeleton; cytoplasmic vesicle; cytoskeleton; dendrite; early endosome; endoplasmic reticulum; lysosome; mitochondrion; nucleus; presynapse; autophagosome; axon; axon cytoplasm; centriole; centrosome; cytoplasm; dendritic spine; growth cone; neuron projection; synaptic vesicle
Genetic constraint (gnomAD): Loss-of-function variants: 47 observed, 45.76 expected, observed/expected ratio (o/e) 1.03, 90% interval 0.81 to 1.31. The upper end of that interval is the gene's LOEUF score, 1.31, which puts it in group 5 of 6, group 1 being the genes least tolerant of losing a copy. Missense variants: 706 observed, 693.7 expected, observed/expected ratio (o/e) 1.02, 90% interval 0.96 to 1.08. Synonymous variants: 307 observed, 300.94 expected, observed/expected ratio (o/e) 1.02, 90% interval 0.93 to 1.12.
Homologues: Orthologues: chimpanzee HAP1 (97% identical), pig HAP1 (70% identical), dog HAP1 (66% identical), mouse Hap1 (58% identical), rat Hap1 (58% identical), tropical clawed frog hap1 (24% identical), zebrafish hap1 (18% identical), Drosophila melanogaster milt (16% identical), Caenorhabditis elegans trak-1 (12% identical). Paralogues in human: TRAK1 (23% identical), TRAK2 (22% identical).
Diseases named in the same sentence as HAP1 in open-access papers:
HAP1 is named in the same sentence as 81 diseases in open-access papers, as found by Europe PMC text mining. Sharing a sentence is not in itself a finding about the gene and the disease. The quoted sentences say what the papers report.
Huntington disease (23 papers, 2012 to 2025). Huntington disease (HD) is a rare neurodegenerative disorder of the central nervous system characterized by unwanted choreatic movements, behavioral and psychiatric disturbances and dementia. "Huntingtin-associated protein 1 (HAP1) is considered a neural interactor of huntingtin, a protein responsible for Huntington’s disease (HD)." (PMID 40766770, 2025). "HAP1 is strongly linked to several neurological diseases, including Huntington’s disease, Alzheimer’s disease, epilepsy, ischemic stroke, and depression." (PMID 38975245, 2024). "In rodents, HAP1 is defective in brain regions such as the striatum, hippocampus, and neocortex, where neuronal loss is most severe in patients with Huntington’s disease (HD)." (PMID 38975245, 2024). "Concerning Huntington’s disease (HD), the huntingtin-associated protein 1 (HAP1) that CCs endogenously express reduces full fusion exocytosis by affecting vesicle docking and controlling fusion pore stabilization." (PMID 36884064, 2023). "Huntingtin-associated protein 1 (Hap1) was initially identified as a brain-enriched protein that binds to the Huntington’s disease protein, huntingtin." (PMID 32581713, 2020). "Huntingtin-associated protein 1 (Hap1) was first identified as an interacting partner of huntingtin (Htt), the protein product of the Huntington’s disease (HD) gene." (PMID 32581713, 2020). "Hap1 (Huntingtin-associated protein 1) was discovered as a binding partner for Huntingtin and is therefore implicated in the neurodegenerative disorder Huntington's disease." (PMID 28973476, 2017). "The HAP1 protein interacts with the huntingtin protein, which is associated with Huntington disease." (PMID 28750619, 2017). "Huntingtin-associated Protein 1 (HAP1) is a ~100 kDa protein that was first identified in a screen for proteins that interact with the Huntington’s disease (HD) gene product, huntingtin (HTT)." (PMID 27737633, 2016). "Successively, an interaction with huntingtin-associated protein 1 (HAP1) was discovered, linking kalirins to Huntington disease (HD)." (PMID 23284848, 2012). "Dysfunction of HAP1 has been linked to the neuropathology in Huntington disease, a disease where cognitive decline and psychiatric symptoms are often prominent." (PMID 22384057, 2012). "Furthermore, Huntington-associated protein 1 (HAP1) interacts with the huntingtin that, when mutated, causes Huntington’s disease (HD); HAP1 reduces full fusion exocytosis by affecting vesicle docking and controlling fusion pore stabilization." (PMID 32178443, 2020). "Huntingtin-associated protein a (Hap1) is an intriguing neuronal-enriched protein that interacts with several disease-related proteins, including huntingtin and Ahi1, whose mutations cause Huntington's disease (HD) and Joubert syndrome, respectively." (PMID 25875952, 2015). "Huntingtin-associated protein 1 (HAP1) was first recognized for its binding to polyglutamine (polyQ)-expanded huntingtin, the causative protein for Huntington’s disease." (PMID 36831801, 2023). "HAP1 was first identified as an interactor of neurodegenerative Huntingtin (Htt), the protein responsible for Huntington disease and was subsequently shown to protect specific neuronal cells from degradation." (PMID 35837121, 2022). "HAP1 was initially recognized as a polyglutamine (polyQ) length-dependent interactor of huntingtin (htt), the gene product responsible for Huntington’s disease." (PMID 33089002, 2020). "HAP1 can inhibit the nuclear translocation of gene products of a number of neurodegenerative diseases such as Huntington’s disease, Machado-Joseph disease and SBMA." (PMID 33089002, 2020). "Similarly, in cellular and mouse models of Huntington’s disease, it was observed that the huntingtin/HAP1/dynactin complex was altered." (PMID 41254423, 2025).
Huntington disease (continued). "In Huntington ́s disease, Htt indirectly regulates REST nuclear trafficking via the interaction of REST/NRSF-interacting LIM domain protein (RILP) and dynactin p150Glued*, an Htt-associated protein 1 (HAP1) bound to the Htt protein." (PMID 31361762, 2019). "In Huntington's disease, Htt regulates REST nuclear trafficking indirectly via the interaction of REST/NRSF-interacting LIM domain protein (RILP) with dynactin p150Glued*, an Htt-associated protein 1 (HAP1) that binds to the Htt protein." (PMID 31361762, 2019). "Interestingly, Ataxin-10 (Atxn10) and Huntingtin-associated protein 1 (Hap1), proteins associated with the neurodegenerative disease spinocerebellar ataxia 10 (SCA10) and Huntington’s disease, respectively, were identified as UBQLN2 interactors." (PMID 27164932, 2016). "However, HAP1 itself has not been directly linked to Huntington disease." (PMID 28750619, 2017). "In addition to Huntington’s disease, previous studies indicated that STB/HAP1 could also have protective effects against neurodegeneration in spinal and bulbar muscular atrophy, spinocerebellar ataxia type 17, Machado-Joseph disease, and Joubert syndrome." (PMID 36831801, 2023). "We also found many differentially expressed genes related to the Huntington disease (HD) pathway in both areas of the MPS II mouse model; among these, Bbc3, Bdnf, Crebbp, Dctn1, Dlg4, Gpx1, Grin1, Grin2b, Itpr1, and Pparg are up-regulated, while Dnaic2, Dnali1, Hap1, and Vdac2 are down-regulated." (PMID 28513549, 2017).
chronic myeloid leukemia (8 papers, 2016 to 2025). "Hap1 is a near haploid human cell line derived from the male, chronic myelogenous leukemia (CML) cell line KBM-7." (PMID 37747131, 2023). "The other one (HAP1) that is derived from a patient with chronic myeloid leukemia is haploid and therefore widely used in CRISPR experiments." (PMID 31212706, 2019). "We chose to use the Hap1 human haploid fibroblastoid cell line, derived from a chronic myelogenous leukemic line KMB-7 isolated from a 39-year-old man with chronic myeloid leukaemia in blast crisis." (PMID 27519690, 2016).
breast carcinoma (7 papers, 1998 to 2024). "In one study, HAP1 overexpression in both breast cancer cell lines (MCF-7 and MDA-MB-231) and gastric cancer cell lines (MKN28 and AGS) significantly inhibited tumor cell growth and proliferation and reduced invasion and migration." (PMID 38975245, 2024). "To test the metabolic switch beyond the HAP1 background, we generated a panel of SHMT2 deficient cell lines for the colorectal cancer cell line HCT116 and breast cancer cell lines MDA-MB-231, SKB3, T47D and MDA-MB-468." (PMID 32366892, 2020). "HAP1 has been shown to have an inhibitory effect on the growth rate of breast cancer cell lines, and is under-expressed in breast cancer tissues." (PMID 27737633, 2016). "We used immunohistochemistry to examine the expression of HAP1 in normal breast and in 102 primary breast carcinomas." (PMID 9569057, 1998). "Notably, HAP1 expression in breast cancer tissues is one-third lower than that in normal breast tissues." (PMID 38975245, 2024). "A similar study revealed that the HAP1 gene could also regulate the radiosensitivity of the breast cancer cell line MCF-7 and promote the apoptosis of MCF-7 cells after radiotherapy." (PMID 38975245, 2024). "This indicates that HAP1 is a potential biomarker in breast cancer." (PMID 38975245, 2024). "We also found that when overexpressed, HA-TRPM7 has the capacity to bind native CNNM proteins in other cell lines (Hela, opossum kidney proximal tubule (OK), RPTEC/TERT1, and HAP1) and that endogenous TRPM7 interacts with native CNNM4 in ZR-75-1 breast cancer cells." (PMID 34928937, 2021).
leukemia (6 papers, 2016 to 2024). A malignant (clonal) hematologic disorder, involving hematopoietic stem cells and characterized by the presence of primitive or atypical myeloid or lymphoid cells in the bone marrow and the blood. "To evaluate the phenotypic effects of CDK8 and CDK19 in other cell lines, we have generated HAP1 leukemia derivatives with the knockout of CDK8, CDK19 or both CDK8 and CDK19 (dKO)." (PMID 37378433, 2023). "Finally, we detected the expression of marker genes of macrophage and NK cells, and found that five genes of FCAR, FCGR3A, PREX1, S100A8 and S100A9 all were significantly overexpressed in the leukemia cells of HAP1 compared with that in the normal stroma cells of HS-5 (p < 0.05)." (PMID 39583114, 2024). "To test whether this effect was PPAR-dependent, we measured proliferation of the haploid human leukemia cell line HAP1, and genetically engineered versions that lack functional proteins PPARα (HAP1 PPARA KO) or PPARγ (HAP1 PPARG KO), after adding arachidonic acid." (PMID 34984327, 2022). "Interestingly, one of the two leukemia cell lines, K562, is clustered with HeLa derived from the cervical tumor, whereas the other, KBM7 and its derivative Hap1, are grouped with normal lymphoid cells, GM12878 and T-cells, suggesting cancer heterogeneity among leukemia cells." (PMID 31828312, 2020).
depression (5 papers, 2015 to 2025). "Therefore, HAP1 may be a potential candidate for understanding the mechanism underlying the depression‐like behavior associated with USP46." (PMID 39482856, 2025). "HAP1 controls postnatal hippocampal neurogenesis and adult depressive behaviors via a novel mechanism, which suggests potential new approaches for depression prevention and therapy." (PMID 38975245, 2024). "The decreased expressions of mRNAs in CUMS-induced depression mice include Slc6a11, Hap1, Gad1, Gad2, Gng4, Slc32a1, Doc2g, Slc32a1, Magel2, Prkcd, Ngfr, Dusp1, Th, Itih3, Cacna2d2, Arc, Mbp, Peg10, Fos, and so on." (PMID 27427907, 2016). "Taken together, our current findings suggest that HAP1 may stabilize 5-HT neurons and enhance or restore 5-HT functions to mitigate depression-like symptoms in PD." (PMID 40766770, 2025). "To see whether camk2a-Hap1 KO mice would behave similarly in the depression tests as the induced Hap1 KO mice, we performed the FST and TST, which demonstrated that camk2a-Hap1 KO mice at 2-month old indeed displayed depressive-like behavior." (PMID 25875952, 2015). "Our results also demonstrate that overexpression of c-kit in the postnatal hippocampus can augment hippocampal neurogenesis and alleviate adult depression, suggesting a new mechanism by which Hap1 regulates postnatal neurogenesis and consequent adult depressive behavior." (PMID 25875952, 2015). "As the involvement of hippocampal neurogenesis in adult depression has been widely demonstrated, we next examined whether Hap1 also regulates hippocampal neurogenesis." (PMID 25875952, 2015). "In conclusion, we have demonstrated a novel role for Hap1 in the regulation of postnatal neurogenesis and adult depressive-like behavior and provided the first genetic model that relates postnatal neurogenesis to adult depression." (PMID 25875952, 2015). "Our results demonstrate critical roles for Hap1 and c-kit in postnatal neurogenesis and adult depressive behavior, and also suggest that genetic variations affecting postnatal neurogenesis may lead to adult depression." (PMID 25875952, 2015). "Intriguingly, it has been reported that HAP1 can stabilize the expression of hypothalamic GR, which is crucial for regulating the HPA axis and alleviating major depression." (PMID 40766770, 2025). "To rule out the possibility that our Hap1 KO mice had any physical impairment that might result in poor performances in depression tests, as well as a locomotor activity assay, we did a rotarod test on both P1 KO and camk2a-Hap1 KO mice; we found no such impairment in either of the KO groups." (PMID 25875952, 2015).
colorectal cancer (3 papers, 2020 to 2025). A primary or metastatic malignant neoplasm that affects the colon or rectum. "DNMT1 ablation in human colorectal carcinoma cells results in mitotic catastrophe and loss of cell viability, whereas HAP1 DNMT1 KO cells show increased DNA damage response and apoptosis but are viable." (PMID 40112032, 2025). "We started with six near-diploid human cell lines that comprise three categories: myeloid leukemia (diploidized HAP1 -[referred to here as dipHAP1] and EEB), colorectal cancer (HCT116 and DLD1), and epithelial noncancer (hTERT-RPE1 and hTERT-HME1)." (PMID 36859339, 2023).
gastric cancer (3 papers, 2021 to 2024). A primary or metastatic malignant neoplasm involving the stomach. "In HAP1-overexpressing gastric cancer cells, glucose deprivation leads to a significant decrease in ATP production and a significant increase in ROS production and triggers oxidative stress, which ultimately results in cell death." (PMID 38975245, 2024). "Furthermore, as a desirable outcome of targeted glucose metabolism for anticancer therapies, glucose deprivation-induced cell death is more pronounced in gastric cancer cells that overexpress HAP1." (PMID 38975245, 2024). "Therefore, in this study, 1,449 FDA-approved drugs were screened to determine whether they could be used as therapeutic agents for the treatment of gastric cancer using growth inhibition assays of HAP1, HAP1 RNF43 KO, and HAP1 PWWP2B KO cells." (PMID 34149925, 2021).
melanoma (3 papers, 2009 to 2021). A malignant, usually aggressive tumor composed of atypical, neoplastic melanocytes. "In these studies the migration of human and mouse melanoma on fibronectin was inhibited by purified T4 and HAP1 bacteriophage preparations." (PMID 19154575, 2009). "The migration of human and mouse melanoma can be inhibited by purified T4 and HAP1 bacteriophage preparations." (PMID 19154575, 2009). "Studying the interactions between T4 and HAP1 phages and cancer cells, antimetastatic activity was demonstrated against a melanoma mouse model and Lewis lung cancer (LLC) model in vivo and inhibition of migration in mouse B16 and human Hs294T melanoma in vitro." (PMID 34445641, 2021). "On the other hand, the difference between T4 and HAP1 interactions with melanomas may simply be undetectable in the types of tests conducted." (PMID 19154575, 2009). "Importantly, HAP1 was also much more effective against melanoma metastases in vivo." (PMID 19154575, 2009). "Due to the lack of observations for the interaction of phages T4 and HAP1, which interacted with murine B16 melanoma cells and LLC, one might conclude that bacteriophages do not necessarily interact with every type of cancer." (PMID 34445641, 2021).